SCHLAP1 (SWI/SNF complex antagonist associated with prostate cancer 1)
Diseases named in the same sentence as SCHLAP1 in open-access papers (continued):
Sharing a sentence is not in itself a finding about the gene and the disease.
prostate carcinoma (continued). "RNAscope of RP tissue from ICC1-7 and an additional extended independent cohort showed increased SCHLAP1 expression in ICC/IDC compared to benign prostate epithelial cells and Gleason pattern 3, Gleason pattern 4 non-ICC (NC) and Gleason pattern 5 prostate cancer." (PMID 36229464, 2022).
benign prostatic hyperplasia (3 papers, 2019 to 2025). A non-cancerous nodular enlargement of the prostate gland. "For instance, observed noticed that the levels of SAP30L-AS1 in exosomes isolated from serum were upregulated in benign prostatic hyperplasia (BPH), while higher SChLAP1 has been recorded in prostate cancer (PC) as compared to BPH and normal control." (PMID 40703556, 2025).
bladder cancer (3 papers, 2017 to 2021). "In bladder cancer, SCHLAP1 acts as a pro-oncogene, and silencing SCHLAP1 induces proliferation of bladder cancer cells, promotes apoptosis, and inhibits cell migration." (PMID 31419958, 2019). "Cell transfected with SChLAP1 siRNA showed growth arrest, apoptosis, and migration inhibition, suggesting oncogenic roles in bladder cancer and a potential therapeutic target." (PMID 29312884, 2017). "SChLAP1 is also overexpressed in bladder cancer compared to paired normal bladder tissues." (PMID 29312884, 2017). "Besides, we observed a strong correlation between SchLAP1 and AC009478.1 expression in TCGA data only for PCa and bladder cancer (R = 0.94 and 0.85, respectively, with p < 2.2e-26), suggesting a possible, still unknown role also for this latter lncRNA in such tumor types." (PMID 34311724, 2021).
glioblastoma (3 papers, 2020 to 2023). The most malignant astrocytic tumor (WHO grade IV). "It has been shown to form a complex with lncRNA SChLAP1 to regulate glioblastoma by activating NF-κB signaling and stabilizing ACTN4." (PMID 35549989, 2022).
prostate tumor (2 papers, 2014 to 2021). "Expected results were obtained that SChLAP1 and CTBP1-AS were upregulated in prostate tumor tissues than that in the non-tumor tissues, while the miR-340-5p were inversely downregulated." (PMID 33589600, 2021).
glioma (1 paper, 2019). A benign or malignant brain and spinal cord tumor that arises from glial cells (astrocytes, oligodendrocytes, ependymal cells). "SCHLAP1 is one of the low-grade glioma immune-related lncRNAs we screened." (PMID 31419958, 2019).
intraductal carcinoma (1 paper, 2017). "Combining histology features of cribriform architecture and intraductal carcinoma with genomic instability or SChLAP1 expression can stratify patients for recurrence more accurately than any parameter alone." (PMID 29312884, 2017). "Interestingly, SChLAP1 RNA-ISH diffuse expression has been observed in the cribriform architecture and intraductal carcinoma and in the adjacent invasive adenocarcinoma." (PMID 29312884, 2017).
cancer (23 papers, 2015 to 2025). A tumor composed of atypical neoplastic, often pleomorphic cells that invade other tissues. "In vitro and in vivo gain-of-function and loss-of-function experiments have shown that SChLAP1 plays a crucial role in cancer cell invasiveness and metastasis, antagonizing the activity of the SWI/SNF chromatin-modifying complex, a multiprotein system able to move nucleosomes at gene promoters." (PMID 29312884, 2017). "Overexpression of the modules led to a notable increase in cancer cell proliferation and invasion, proving their functional significance on the oncogenicity of SChLAP1." (PMID 39975023, 2025). "Overexpression of the modules led to a notable increase in cancer cell proliferation and invasion, proving their functional significance in the oncogenicity of SChLAP1." (PMID 40683595, 2025). "Both OPN and SChLAP1 are molecules that effectively promote the proliferation and migration of cancer cells." (PMID 38342891, 2024). "Collectively, these findings support that ICC/IDC cancer cells have high inter-patient heterogeneity, but commonly upregulate SCHLAP1 and TNFα signaling via NFĸB pathway member JAG1." (PMID 36229464, 2022). "The authors introduced a new term, nimbosus, characterized by the combination of pathological, molecular, and micro-environmental events, including intraductal carcinoma and cribriform architecture, genomic instability, SCHLAP1 expression, and hypoxia." (PMID 34576134, 2021). "These molecules show promise as prognostic biomarkers; SChLAP1 and XPLAID have elevated expression in both tumor and normal associated tissues of aggressive cancers, and AC009014.3 has elevated expression in tumors of indolent cancers." (PMID 29723810, 2018). "In our results, SChLAP1 and XPLAID exhibited significant differences of expression in normal tissues associated with aggressive cancer." (PMID 29723810, 2018). "Specifically, SChLAP1 has previously been shown to be an effective biomarker of aggressive cancers in such urine analysis." (PMID 29723810, 2018). "All such findings show multiple interactions between SChLAP1 and factors involved in oncogenesis and cancer progression and explain the mechanism through which SChLAP1 promotes migration and invasion of PCa." (PMID 29312884, 2017). "Using mRNA abundance analyses and assessing >25,000 genes, they found that SChLAP1 was surprisingly the only gene with more than threefold higher expression in IDC/CA+ compared to IDC/CA− cancers." (PMID 29312884, 2017). "Since SChLAP1 is remarkably enriched in the nucleus of the cells, we assume that SChLAP1 may be engaged in the transcriptional modulation of upstream regulators of the proliferative and invasive phenotype of cancer cells." (PMID 39975023, 2025). "In summary, our study demonstrates that the proliferative and invasive properties of SChLAP1 are driven by its modular architecture, particularly its terminal modules, which may represent potential targets for small-molecule-based cancer therapies." (PMID 39975023, 2025). "We found no other report that SChLAP1 has elevated expression specifically in normal tissues associated with high-grade cancer; this expression difference in tissue that is readily available to urine analysis likely contributed to its success as a biomarker for that analysis." (PMID 29723810, 2018). "Together with published reports of cancer metastasis-related lncRNAs, such as lncRNA-ATB, SChLAP1, NKILA, and PNUTS, our study confirms the regulatory roles of lncRNAs in EMT and cancer metastasis." (PMID 30979372, 2019). "In light of the prevalent and conserved roles of EZH2, DNMT3a, lncRNAs, and miRNAs in epigenetic regulation, the potential implications of the SChLAP1/EZH2/miRNA axis and the feedback loop between miRNAs and DNMTs in other human cancers also deserve further explorations." (PMID 33589600, 2021).
cancer (continued). "Furthermore, SChLAP1 knockdown determined a decrease of MMP-9, MMP-14, and VEGF expressions both in vitro and in vivo, confirming its involvement in cancer invasiveness and metastasis." (PMID 29312884, 2017). "Like the recently identified PCAT1, SChLAP1 and PCAT29, the expression of some of the novel EPCATs is functionally relevant and therefore, cancer-associated lncRNAs should not entirely be seen as transcriptional noise due to aberrant regulation." (PMID 25686826, 2015). "However, the molecular mechanism behind SChLAP1’s oncogenic role in cancer development is not well understood." (PMID 39975023, 2025). "With the rise of studies on the functional properties of lncRNAs, it has been verified that lncRNAs can efficiently affect the biological processes of cancers, some of which may serve as tumor or metastasis inhibitors, such as GAS5 and MEG3, while others may promote oncogenesis, such as SChLAP1." (PMID 32694942, 2020). "Using RNA in situ hybridization, we previously found that SChLAP1 was not only over-expressed in CR/IDC structures but also in adjacent non-cribriform cancer glands suggesting that it represents a field effect during tumour progression and not a specific characteristic of CR/IDC growth." (PMID 29295717, 2018).
tumor (22 papers, 2015 to 2025). "Transcriptomic analysis also identified genes associated with tumour aggression in mpMRI-visible tumours, such as noncoding RNA SCHLAP1 (linked to prostate cancer progression), several small nuclear RNAs, and angiogenesis factor VEGF." (PMID 33000006, 2020). "They found that the long non-coding RNA SChLAP1, which has been associated with tumour progression, was significantly higher in CR/IDC, and that CR/IDC growth was associated with hypoxia." (PMID 29295717, 2018). "For example, an LTR12C locus acts as promoter for the lncRNA SWI/SNF complex antagonist associated with prostate cancer 1 (SchLAP1), which is overexpressed in about 25% of prostate cancers, where it suppresses the anti-tumor activity of the chromatin-modifying SWI/SNF complex." (PMID 39887236, 2025). "SchLAP1 depletion and overexpression experiments revealed that this lncRNA is essential for tumor invasiveness and metastasis in vivo." (PMID 39887236, 2025). "SchLAP1 is overexpressed in a subset of PCa where it antagonizes the tumor-suppressive function of the SWI/SNF complex and can independently predict poor outcomes." (PMID 34311724, 2021). "In agreement with this, our results show higher accessibility to SCHLAP1 in Gleason pattern ≥4 tumours." (PMID 34911933, 2021). "Both the test of SChLAP1 (candidate C2) and the novel extended region of this transcript (candidate C6) showed elevated expression in highly aggressive tumor samples." (PMID 29723810, 2018). "The mechanism of SChLAP1 is direct binding to hSNF5, which can antagonize tumor suppressive functions of the SWI/SNF complexes by decreasing their genomic binding." (PMID 28212646, 2017). "By impairing the proper SWI/SNF regulation of gene expression, SChLAP1 antagonizes tumor suppressive function of the SWI/SNF complexes and promotes tumor cell invasion and metastasis." (PMID 28634418, 2017). "LncRNA SChLAP1 (SWI/SNF complex antagonist associated with prostate cancer 1) is upregulated in NSCLC and promotes NSCLC cell proliferation, migration, and invasion, while its knockdown represses tumor growth and metastasis in vivo." (PMID 37686426, 2023). "Therefore, SChLAP1 promotes tumor cell invasion and metastasis by binding and impairing proper SWI/SNF regulation of gene expression." (PMID 28212646, 2017). "Similarly, SChLAP1 was significantly overexpressed in metastatic cancers from a cohort of 1008 patient tissues, and was shown to promote tumor cell invasion and metastasis." (PMID 26690121, 2015). "Interestingly, high SChLAP1 expression is associated with lethal PCa among patients with non-advanced clinical tumor stage." (PMID 29312884, 2017). "Mechanistically different from the lncRNAs above, SChLAP1 regulates the chromatin status by antagonizing SWI/SNF, a tumor suppressive nucleosome remodeling complex, a homolog of the yeast SWItch/Sucrose Non-Fermentable complex." (PMID 26690121, 2015). "In summary, SChLAP1 binds to AUF1, reducing the interaction between AUF1 and the PD-L1 3’UTR and thus increasing PD-L1 mRNA stability and expression, which in turn represses CD8+ T cell function and facilitates tumor cell immune escape." (PMID 37686426, 2023). "Some of them are under investigation such as circulating tumor cells (CTCs), PTEN, androgen receptor variants, long non-coding RNAs such as HOX transcript antisense intergenic RNA, SChLAP1 and MaLAT-1, and several miRNAs such as miRNA-141 and miRNA-301a." (PMID 37740236, 2023). "Similarly, the tumor migration capacity of DU145 and LNcap cells were significantly repressed by SChLAP1 knockdown, which was also completely abrogated by DNMT3a overexpression." (PMID 33589600, 2021). "Finally, our SR only evaluated blood tests and did not evaluate PSA derivatives, circulating tumor cells, SCHLAP1, other long non-coding RNA or genomic classifiers." (PMID 38672176, 2024).
tumor (continued). "However, using SChLAP1 as prognostic test, investigators have obtained a sensitivity around 24% and a specificity of 94% in the group of non-advanced clinical tumor stage and in the group with a 6–7 GS." (PMID 29312884, 2017). "Mechanistically, SChLAP1 interacts with and antagonizes SWItch/Sucrose Non-Fermentable (SWI/SNF), a chromatin remodeling complex that exhibits tumor-suppressive activity, thus SChLAP1 overexpression promotes cell invasion and metastasis." (PMID 33672595, 2021).
SCHLAP1 also shares sentences with these, for which no sentence is quoted: breast carcinoma (1 paper); colon cancer (1); hereditary prostate cancer (1); lung carcinoma (1); metastatic disease (1); metastatic prostate carcinoma (1); prostate adenocarcinoma (1); small cell lung carcinoma (1).